TPMT (thiopurine S-methyltransferase)
Diseases named in the same sentence as TPMT in open-access papers (continued):
Sharing a sentence is not in itself a finding about the gene and the disease.
leukopenia (continued). "When investigated by the TPMT*1/*3C genotype, the heterozygous patients (10/13; 76.92%) more frequently presented with leukopenia (WBC < 2000 cell/mm3) when compared with homozygous wild type patients (39/87; 44.83%) with an OR of 4.10 (95% CI, 1.06–15.95, p = 0.031)." (PMID 34442427, 2021). "TPMT polymorphisms are less common in Asians than in Caucasians; even when leukopenia rates are higher, therefore genotyping TPMT in Asians is not so useful." (PMID 34336887, 2021). "A heterogeneous distribution of TPMT-VNTR alleles among ancestral populations may explain the loss of the correlation between Native American ancestry and the total number of leukopenia events." (PMID 33424606, 2020). "There is a significant negative correlation between the number of leukopenia events and Native American ancestry in patients without TPMT and/or NUDT15 variants." (PMID 33424606, 2020). "Patients carrying more than 5 A repeats present a significant higher number of leukopenia events among patients without TPMT and/or NUDT15 variants." (PMID 33424606, 2020). "The aim of this work is to analyze the TPMT-VNTR in ALL pediatric patients from Uruguay and determine its association with 6-MP hematological toxicity (measured as the number of leukopenia events and 6-MP cumulative dose) in the maintenance phase; taking individual genetic ancestry into account." (PMID 33424606, 2020). "Finally, the combination of NUDT15, TPMT, and CYP2A7 variants improves predictive sensitivity of 6MP-induced leukopenia from 70.7% to 85.4%, but decreases the specificity (91.7% vs. 70.7%)." (PMID 32265697, 2020). "The association between risk groups and the number of leukopenia events remains significant only in the subsample without TPMT and/or NUDT15 variants." (PMID 33424606, 2020). "Whether 6MP-induced leukopenia can be explained by these variants (besides those in NUDT15 and TPMT) is largely unknown, particularly in patients with NUDT15wt/wtTPMTwt/wt genotype." (PMID 32265697, 2020). "We agree with the authors’ conclusions and, according to our data, the search for TPMT gene mutations before starting azathioprine therapy is not useful to predict adverse events such as leukopenia, pancreatitis, hepatitis, or nausea and vomiting." (PMID 31387318, 2019). "Thus, the clinical value of predicting leukopenia by identifying TPMT genotype in East Asian population was hindered by the low frequency of the risk allele." (PMID 29720126, 2018). "Low mutant frequency of TPMT*3C in Asian population suggested this gene may have limited prediction value for AZA-induced leukopenia in Chinese patients." (PMID 29867468, 2018). "The FDA recommend TPMT gene testing to prevent AZA-induced leukopenia before AZA treatment." (PMID 29867468, 2018). "Association of leukopenia with NUDT15 R139C and TPMT*3C genotypes." (PMID 29867468, 2018). "Furthermore, in an exploratory analysis, genetic variants in TPMT, ITPA, and NUDT15 were compared and screened to determine the optimal risk prediction of 6-MP-induced leukopenia." (PMID 29720126, 2018). "In light of results indicating the absence or low frequency of the TPMT gene in Japanese populations, there must be other genetic variations that could explain the frequent thiopurine-induced leukopenia in East Asian populations." (PMID 29192347, 2018). "The risk of leukopenia according to NUDT15 and TPMT genotype." (PMID 29206869, 2017). "Inadequate TPMT activity results in excessive accumulation of the active TGN, leading to dose-dependent marrow suppression and a risk of infection, whereas NUDT15 variants are associated with severe early-onset leukopenia, gastrointestinal toxicity, and alopecia even at moderate doses." (PMID 41446785, 2025).
leukopenia (continued). "There were only two (1.8%) patients with heterozygous mutations of TPMT*3C, and neither of them exhibited myelosuppression; however, among TPMT*3C wild-type allele carriers, 15 (13.5%) patients suffered leukopenia, 34 (30.6%) suffered thrombocytopenia, and 10 (9.0%) experienced neutropenia." (PMID 33846471, 2021). "Even though we found a significant negative correlation between the total number of leukopenia events and Native American ancestry in patients without TPMT and/or NUDT15 variants, this correlation was no longer significant when risk groups were taken into consideration (p = 0.120)." (PMID 33424606, 2020). "However, whether the TPMT and NUDT genotypes were associated with leukopenia in these PBC-AIH patients is unknown." (PMID 30155449, 2018). "However, TPMT genotypes were shown not to be associated with leukopenia in the Japanese and TPMT deficiency fails to explain the higher incidence of adverse reactions in patients with IBD in East Asia." (PMID 29923122, 2018). "In this study, we replicated the finding that TPMT*3C is strongly associated with 6-MP tolerance, but more importantly described a NUDT15 c.415C > T variant associated with a substantially elevated risk of 6-MP-associated leukopenia in Chinese children with ALL." (PMID 29720126, 2018). "In addition to the previously known TPMT mutation, NUDT15 (nucleoside diphosphate-linked moiety X-type motif 15) genetic variants have been recently identified to be strongly associated with thiopurine-induced leukopenia in Asians." (PMID 29206869, 2017). "In addition to the TPMT polymorphism (TPMT *1/*3C), NUDT15 p.Arg139Cys (nucleoside diphosphate-linked moiety X-type motif 15, p.Arg139Cys variant) may be associated with the appearance of leukopenia." (PMID 36553655, 2022). "Interestingly, patients with heterozygous genotype of NUDT15 but not the TPMT variant may have a higher risk to experience 6MP-induced leukopenia when they also carry risk allele of rs73032311." (PMID 32265697, 2020). "Our study was aimed to investigate NUDT15 R139C, TPMT*3C, 6-TGN levels and explore their influence on AZA-induced leukopenia in Chinese autoimmune diseases (except IBD), retrospectively." (PMID 29867468, 2018). "The aim of this study was to investigate the influence of NUDT15 R139C, thiopurine S-methyltransferase (TPMT), and 6-TGN on azathioprine (AZA) induced leukopenia in Chinese autoimmune patients." (PMID 29867468, 2018). "No TPMT genetic variants were genotyped in these 12 patients, but heterozygous NUDT15 R139C genotypes were found in the 2 patients who experienced leukopenia (data not shown)." (PMID 30155449, 2018). "In logistic regression, TPMT genotype and activity were not significantly related to leukopenia during azathioprine therapy." (PMID 29630648, 2018). "Occurrence of mild or moderate leukopenia also did not significantly differ between tertiles of TPMT activity." (PMID 29630648, 2018). "However, there are studies reporting patients of different ethnicities who had leukopenia and did not have the TPMT variant allele, suggesting that the TPMT polymorphism does not efficiently predict AZA-induced leukopenia." (PMID 37959208, 2023). "Therefore, compared with TPMT*3C and ITPA 94C>A, the detection of NUDT15 c.415C>T in the Chinese population may have better predictive value for AZA-induced myelosuppression with leukopenia and neutropenia as the primary manifestations." (PMID 33846471, 2021). "The variants of TPMT*3C and ITPA c.94C>A were not related to leukopenia." (PMID 34660484, 2021). "The effect of TPMT genotype-guided thiopurine administration on hematologic adverse drug reactions, such as leukopenia and thrombocytopenia, between genotyped and non-genotyped arms was not significantly different (frequency: 7.4% versus 7.9%; relative risk: 0.93)." (PMID 31052430, 2019).
leukopenia (continued). "Paradoxically, thiopurine-induced leukopenia is more common in East Asian individuals, and many patients who develop leukopenia after receiving AZA treatment cannot be reliably identified by genotyping or TPMT activity measurements because these patients have normal or near normal TPMT activity." (PMID 31024313, 2019). "TPMT genotype and activity were not independent predictors of relapse, and could not predict leukopenia or other adverse effects from azathioprine." (PMID 29630648, 2018). "However, TPMT genotype was not shown to be correlated with the incidence of leukopenia (p = 0.95)." (PMID 29867468, 2018).
acute lymphoblastic leukemia (34 papers, 2012 to 2024). Leukemia with an acute onset, characterized by the presence of lymphoblasts in the bone marrow and the peripheral blood. "NUDT15 and TPMT variants are strong genetic determinants of thiopurine-induced hematological toxicity that results in therapeutic failure in pediatric acute lymphoblastic leukemia (ALL)." (PMID 32611418, 2020). "Low TPMT activity is associated with severe toxicity in acute lymphoblastic leukaemia patients." (PMID 37202783, 2023). "The associations of NUDT15 and TPMT genetic variants with 6-mercaptopurine (6-MP) intolerance have been very well established in pediatric acute lymphoblastic leukemia (ALL)." (PMID 32611418, 2020). "In population-based studies, TPMT, TOR2A, KIF11, and EIF5A were reported to be associated with prognosis in other tumours, such as childhood acute lymphoblastic leukaemia, ovarian cancer, breast cancer, and colorectal cancer." (PMID 35421138, 2022). "Nudix Hydrolase 15 (NUDT15) and Thiopurine S-Methyltransferase (TPMT) are strong genetic determinants of thiopurine toxicity in pediatric acute lymphoblastic leukemia (ALL) patients." (PMID 31244663, 2019). "Thiopurine methyltransferase (TPMT) is an enzyme involved in the metabolism of 6‐mercaptopurine (6‐MP) that is used for the treatment of acute lymphoblastic leukemia." (PMID 30003187, 2018). "The genotyping of thiopurine S-methyltransferase (TPMT) in acute lymphoblastic leukemia (ALL) patients before treatment with 6-mercaptopurine is useful to select the correct dose based on genetics before the first drug intake." (PMID 30018749, 2018). "As an example, in acute lymphoblastic leukemia patients the metabolizer status of thiopurine methyltransferase (TPMT) must be considered when calculating the initial drug dose of mercaptopurine (6-MP) to ensure proper treatment and avoid fatal toxicity." (PMID 25901276, 2015). "Similarly, TPMT is involved in the metabolism of 6-mercaptopurine (6-MP), which is often administered in acute lymphoblastic leukemia (ALL); however, few ALL patients were enrolled in our study, and only one received 6-MP." (PMID 34572750, 2021). "The influence of thiopurine methyltransferase (TPMT) genotype on treatment outcome was investigated in the United Kingdom childhood acute lymphoblastic leukaemia trial ALL2003, a trial in which treatment intensity was adjusted based on minimal residual disease (MRD)." (PMID 25940902, 2015). "The level of expression of the enzyme thiopurine methyltransferase (TPMT) is an important determinant of the metabolism of thiopurines used in the treatment of acute lymphoblastic leukemia (ALL)." (PMID 24734162, 2014). "Despite the impact of homozygous CRIM1 on thiopurine toxicity, several patients with wild-type NUDT15, TPMT, and CRIM1 experience thiopurine toxicity, therapeutic failure, and relapse of acute lymphoblastic leukemia (ALL)." (PMID 33958640, 2021). "One approach taken in pediatric acute lymphoblastic leukemia (ALL) relates to TPMT." (PMID 35582583, 2019). "For children with acute lymphoblastic leukaemia (ALL) treated with mercaptopurine, those individuals with lower TPMT activities and/or higher TGN levels have a lower relapse‐risk." (PMID 25441457, 2015). "We have recently demonstrated that TPMT and ITPA genotypes constitute a multilocus genotype of pharmacogenetic relevance for children with acute lymphoblastic leukemia (ALL) receiving thiopurine therapy." (PMID 23335936, 2012). "Examples of pharmacogenomics and personalized medicine include treatment for certain conditions like blood clotting disorders (warfarin (blood thinner), genetic variability, acute lymphoblastic leukemia (ALL), and thiopurine methyltransferase (TPMT) testing) in leukemia treatment." (PMID 39328627, 2024).
inflammatory bowel disease (28 papers, 2013 to 2025). A spectrum of small and large bowel inflammatory diseases of unknown etiology. "Patients with leukemia or inflammatory bowel disease (IBD) who carry a TPMT mutation, especially those with biallelic mutations, can experience myelosuppression when undergoing treatment with thiopurine medications such as azathioprine and mercaptopurine." (PMID 31623616, 2019). "Polymorphisms of Thiopurine S-methyltransferase (TPMT) are known to be associated with leukemia, inflammatory bowel diseases, and more." (PMID 36344599, 2022). "We tested this method using the levels of enzymatic activity of thiopurine S-methyltransferase (TPMT) that is involved in the metabolism of thiopurine drugs used in inflammatory bowel diseases for example." (PMID 24385893, 2013). "TPMT is an enzyme that took an important effect in the metabolism of immunosuppressant azathioprine and mercaptopurine drugs mainly in rheumatoid arthritis, pediatric leukemia, and inflammatory bowel disease." (PMID 34322485, 2021). "TPMT, together with nudix hydrolase, is the most important enzyme for thiopurine metabolism, and TPMT activity is inversely correlated with the levels of the active metabolites, as observed in children with leukemia and in patients with inflammatory bowel diseases." (PMID 38004461, 2023). "Demographics, clinical, and the thiopurine S-methyltransferase (TPMT)/Nudix Hydroxylase 15 (NUDT15) genotypes in 140 patients with inflammatory bowel disease (IBD)." (PMID 35991642, 2022). "TPMT plays a significant role in the biotransformation of clinically important thiopurine drugs used in the management of leukaemia, inflammatory bowel diseases (IBD), rheumatic diseases and dermatological conditions." (PMID 29444714, 2018).
leukemia (26 papers, 2004 to 2025). A malignant (clonal) hematologic disorder, involving hematopoietic stem cells and characterized by the presence of primitive or atypical myeloid or lymphoid cells in the bone marrow and the blood. "The TPMT gene encodes the TPMT enzyme, which is pivotal in metabolizing thiopurine drugs used in the treatment of various conditions such as autoimmune diseases and leukemia." (PMID 40183077, 2025). "The TPMT gene encodes the thiopurine S-methyltransferase enzyme, which is responsible for the metabolism of thiopurine drugs widely used for the treatment of leukemia and autoimmune disorders." (PMID 37759556, 2023). "Some of these candidate-gene studies have led to relevant findings with an impact on clinical practice (e.g. TPMT polymorphism-associated mercaptopurine intolerance in leukemia)." (PMID 37018234, 2023). "TPMT was chosen due to the known association of its polymorphisms with the disease progression and treatments of several dangerous diseases including leukemia and IBD (Crohn's disease and ulcerative colitis) (IBD)." (PMID 36344599, 2022). "Among Arabs, some studies have evaluated the frequencies of the known star alleles in TPMT in healthy or pediatric leukemia participants from Egypt, Tunisia, Morocco, Jordan, and Lebanon78–82." (PMID 33277594, 2020). "The association of TPMT with thiopurines toxicity, especially 6-MP in pediatric leukemia, has been the role model of PGx implication in the clinic." (PMID 33277594, 2020). "For example, patients with certain variants of TPMT, a thiopurine methyltransferase, are known to exhibit severe toxicity to the most common leukemia chemotherapy drug, thiopurine." (PMID 29077858, 2019). "The dosage of the drug for their treatment is thus currently adjusted, based on TPMT variant screening, to avoid the toxicity and treat leukemia effectively." (PMID 29077858, 2019). "A seminal example of the importance of pharmacogenomics is the story of acute childhood leukaemia and variants in the thiopurine S-methyltransferase (TPMT) gene." (PMID 14970847, 2004). "Pediatric leukaemia patients with TPMT variants, who receive cranial irradiation, have a greater likelihood for secondary brain tumours." (PMID 14970847, 2004). "Therefore, SNPs of TPMT can be crucial in the disease progression and treatments associated with leukemia, IBD, and more." (PMID 36344599, 2022). "PACSIN2 polymorphism was shown to associate with TPMT activity, and knocking down PACSIN2 in a leukemia cell line reduced TPMT activity." (PMID 34990060, 2022). "Knowing the relevant TPMT and NUDT15 polymorphisms early in therapy allows appropriate chemotherapeutic dosing, prior to onset of toxicity, which were identified in 12% of leukemia cases in this cohort." (PMID 31133068, 2019). "Secondly, the testing of leukaemia patients for the thiopurine S-methyltransferase (TPMT) gene is a practical use of genetic testing to determine the ideal drug dose." (PMID 30248964, 2018). "Another enzyme called TPMT (thiopurine methyltransferase) plays an important role in the chemotherapy treatment of a common childhood leukemia by breaking down thiopurines." (PMID 22461867, 2009). "Of the known human MTases, only a few are known to metabolize drugs and these include catecholamine O-methyltransferase (COMT), which can metabolize levodopa and thiopurine S-methyltransferase (TPMT), which metabolizes thiopurines used in the treatment of leukemia." (PMID 38076968, 2023). "Finally, variant testing in TPMT and NUDT15 was included in leukemia/lymphoma cases, given that certain polymorphisms in these genes lead to altered metabolism of the therapeutic agents, thioguanine and mercaptopurine." (PMID 31133068, 2019). "This is exemplified with genotyping of thiopurine S-methyltransferase (TPMT), which inactivates thioguanine, to avoid serious toxicity in childhood leukemias." (PMID 18547414, 2008).
leukemia (continued). "PACSIN2 moreover may affect TPMT activity: indeed, the knock-down of PACSIN2 mRNA in human leukemia cells NALM6 resulted in significantly lower TPMT expression and enzymatic activity that can in turn result in a higher tGTP availability and Rac-1 inhibition." (PMID 35582727, 2019). "TPMT enzyme activity could be measured in red blood cells directly or in serum, Although in patients who have received recent blood transfusions or in the patients with leukemia, because of atypical hematopoiesis, the result will not reflect the true enzymatic activity of the patient." (PMID 32944042, 2020).